HSPA5 (heat shock protein family A (Hsp70) member 5)
Diseases named in the same sentence as HSPA5 in open-access papers (continued):
Sharing a sentence is not in itself a finding about the gene and the disease.
leukemia (21 papers, 2009 to 2024). A malignant (clonal) hematologic disorder, involving hematopoietic stem cells and characterized by the presence of primitive or atypical myeloid or lymphoid cells in the bone marrow and the blood. "The detachment of the chaperone HSPA5 from the luminal portion of the ER integral membrane proteins EIF2AK3, ERN1, and ATF6 is a crucial process in the activation of ER stress in human leukemia and bladder carcinoma cell lines." (PMID 39000233, 2024). "Interestingly, knockdown of HSPA5 blocks downstream PI3K/AKT signaling and has been reported to decrease prostate and leukemia tumorigenesis." (PMID 25301734, 2014).
non-small cell lung carcinoma (21 papers, 2013 to 2025). A group of at least three distinct histological types of lung cancer, including non-small cell squamous cell carcinoma, adenocarcinoma, and large cell carcinoma. "Prior studies have implicated that EPB41L3 can attenuate epithelial-mesenchymal transition (EMT) and metastasis by suppressing heat shock protein 5 (HSPA5) in non-small cell lung cancer (NSCLC)." (PMID 33323539, 2020). "Moreover, two non-small cell lung cancer models displayed a different effect on HSPA5 expression in response to cisplatin induced senescence." (PMID 39472623, 2024). "The interaction between Hspa5 and EEF2 promotes the overexpression of PRMT7 in non-small cell lung cancer cells, thus regulating cancer cell migration and colony formation." (PMID 34437425, 2021).
Parkinson disease (21 papers, 2012 to 2025). A progressive degenerative disorder of the central nervous system characterized by loss of dopamine producing neurons in the substantia nigra and the presence of Lewy bodies in the substantia nigra and locus coeruleus. "SQSTM1 and HSPA5 dysregulation has been implicated in neurodegenerative disorders, such as Alzheimer’s disease and Parkinson’s disease." (PMID 37059365, 2023). "Previous studies have confirmed that in many cell and animal models of Parkinson's disease, the expression of HSPA5 and other UPR proteins is elevated." (PMID 40415257, 2025). "HSPA5 and AT1-blockers have been previously linked to α-synuclein pathology and Parkinson’s disease, showing the relevance of our findings." (PMID 38295113, 2024). "The results of the KEGG pathway enrichment analysis indicated that the ferroptosis-related DEGs were found to be associated with protein processing in the endoplasmic reticulum and Parkinson’s disease pathways, including Hspa5." (PMID 39343514, 2024). "Grp78 (also known as HSPA5) is important for endoplasmic reticulum (ER) protein folding; it was found to play a neuroprotective role in a rat model of Parkinson disease and was also identified as a new binding partner of spartin, mutations in which can cause SPG20." (PMID 30061306, 2018). "The KEGG findings, revealing the downregulation of Hspa5, may indicate a correlation between noise-induced cognitive decline and endoplasmic reticulum dysfunction, highlighting a potential link to the development of Parkinson." (PMID 39343514, 2024). "Furthermore, it is crucial to note that high abundant proteins were linked to a variety of diseases like Pathways of neurodegeneration-multiple diseases (CSNK2A2, HSPA5, etc.; p-value = 5.34E-08) and Parkinson’s disease (LOC101906363, etc.; p-value = 3.94E-07)." (PMID 36891514, 2023). "Weakening of Hspa5 gene activity did not affect the phenotypic manifestations of 6-OHDA-induced parkinsonism." (PMID 36614266, 2023). "From the Parkinson’s disease KEGG enrichment result, five of differently expressed piRNAs-aligned genes (NDUFA4, CALM3, UCHL1, CALM2, and HSPA5) in the prefrontal cortex (15 genes) overlapped with differently expressed piRNAs-aligned genes in the amygdala (16 genes)." (PMID 35269612, 2022). "In the present study, we investigated the involvement of the chaperone protein BiP (also known as GRP78 or Hspa5), a master regulator of intracellular proteostasis, in two mouse models of neurodegenerative diseases: amyotrophic lateral sclerosis (ALS) and Parkinson’s disease (PD)." (PMID 34830414, 2021).
osteosarcoma (20 papers, 2013 to 2025). A usually aggressive malignant bone-forming mesenchymal neoplasm, predominantly affecting adolescents and young adults. "Targeting HSPA5 was reported to sensitize reactive oxygen species (ROS) osteosarcoma cells to the therapy of pyropheophorbide-α methyl ester-mediated photodynamics." (PMID 37275848, 2023). "Signaling pathways in CDK7/HSPA5 could contribute to tumor growth, invasion, and metastasis of osteosarcoma." (PMID 37275848, 2023). "Down regulation of HSPA5 can promote ANXA1 and repress PSAT1 expression, which inhibiting the osteosarcoma cell proliferation and inducing cell apoptosis." (PMID 34412642, 2021). "Suppression of HSPA5 effectively upregulated ANXA1 and inhibited PSAT1, resulting in osteosarcoma cell proliferation arrest and apoptosis." (PMID 33291071, 2020). "Instead of transactivating HSPA5 in OS cells 7, 8, ATF4 negatively regulates GRP78 transcription in BTZ-resistant OS cells, thus reinforcing the therapeutic effect of BTZ by the dual targeting of GRP78 and RET in the context of osteosarcoma chemoresistance." (PMID 31534554, 2019).
cervical carcinoma (18 papers, 2012 to 2025). A carcinoma arising from either the exocervical squamous epithelium or the endocervical glandular epithelium. "The LTM pathway, which regulates immune cell trafficking across the endothelial barrier, is disrupted in HPV-positive cervical cancer due to the reduced expression of key genes such as HSPA5, CTNNB1, and NPM1." (PMID 41465546, 2025). "This study provides novel insights into HPV-driven immune evasion in cervical cancer, identifying key immune-related hub genes, including HSPA5, CTNNB1, and NPM1, which are downregulated in HPV-positive tumors." (PMID 41465546, 2025). "Targeting key genes in the LTM pathway, such as HSPA5 and CTNNB1, could offer novel approaches to enhance immune cell infiltration and restore immune surveillance in HPV-positive cervical cancer." (PMID 41465546, 2025). "Although the identified immune-related hub genes (HSP90AA1, CTNNB1, NPM1, HSPA5, and HIF1A) were significantly downregulated in HPV-positive cervical cancer, none of them demonstrated a statistically significant correlation with overall survival in the TCGA-CESC cohort." (PMID 41465546, 2025).
head and neck cancer (18 papers, 2010 to 2025). A primary or metastatic malignant neoplasm affecting the head and neck. "The downregulation of Hsp70 protein 5 (HspA5) in isolated head and neck cancer stem cells (HN-CSCs) is related with reduction in self-renewal properties and inhibition of tumorigenicity." (PMID 36286039, 2022). "For instance, the Search page enables the GRN investigation and expression profiling of TFs and target genes (e.g. TF HSPA5 in head and neck cancer), while the Browse page allows examining the detailed information of all identified GRNs in each condition." (PMID 33151298, 2021). "In head and neck cancer, MUL1 induces the ubiquitination of HSPA5 at lysine 446, which triggers cell apoptosis." (PMID 36982218, 2023).
nasopharyngeal carcinoma (18 papers, 2010 to 2025). A carcinoma arising from the nasopharyngeal epithelium. "By mediating the HSPA5-mediated autophagy and AKT/mTOR axis, radiosensitizer exosomal miR-197-3p was reported to inhibit nasopharyngeal carcinoma (NPC) progression and radioresistance." (PMID 37275848, 2023).
Sepsis (17 papers, 2008 to 2025). Sepsis is defined as life-threatening organ dysfunction caused by a dysregulated host response to infection. "Hspa5 is an Hsp70, which is associated with cytoprotection, anti-apoptosis, and anti-inflammation, and has been associated with immune response to sepsis." (PMID 18421376, 2008).
colitis (15 papers, 2015 to 2025). Inflammation of the colon. "In B cells, there was upregulation of transcripts involved in protein synthesis and endoplasmic reticulum stress, such as Calr, Hspd1, Hspa5, in keeping with B cells adopting a secretory state in CPI-induced colitis." (PMID 37872166, 2023). "HSPA5 showed higher expression in healthy than NEC-affected intestinal specimens of infants, and elevated HSPA5 also protected mice against colitis." (PMID 25668313, 2015).
diabetic nephropathy (15 papers, 2014 to 2025). "Up-regulation of HYOU1 and HSPA5 was found in the tubular epithelia of patients with diabetic nephropathy compared with control kidneys." (PMID 37569434, 2023). "A recent study showed that HSPA5 can also be involved in diabetic nephropathy by targeting RhoA and activating the PI3k/Akt pathway." (PMID 35935760, 2022).
pancreatic ductal adenocarcinoma (15 papers, 2015 to 2025). An infiltrating adenocarcinoma that arises from the epithelial cells of the pancreas. "Here, we report that E1A binding protein P300 (EP300) acetyltransferase promotes ferroptosis in human pancreatic ductal adenocarcinoma (PDAC) cells via the acetylation of heat shock protein family A (Hsp70) member 5 (HSPA5), also known as GRP78 or BIP) on the site of K353." (PMID 37696842, 2023). "Previously, HSPA5 is found to negatively regulate the ferroptosis in human pancreatic ductal adenocarcinoma, and the HSPA5-GPX4 pathway could regulate ferroptosis resistance and inhibit the anticancer activity of gemcitabine." (PMID 36193502, 2022). "For example, in human pancreatic ductal adenocarcinoma (PDAC) cells, HSPA5 negatively regulates ferroptosis through the HSPA5‐GPx4 signalling pathway, thereby mediating resistance to ferroptosis." (PMID 38494858, 2024). "In human pancreatic ductal adenocarcinoma cells (PDAC), HSPA5 negatively regulates ferroptosis of PDAC cells through HSPA5-GPX4 signaling pathway, and mediates resistance to ferroptosis." (PMID 35478955, 2022). "This study focused on improving the gemcitabine sensitivity in pancreatic ductal adenocarcinoma (PDAC) by targeting ATF4/HSPA5/GPX4 axis, while the exact molecular mechanism was not deeply studied." (PMID 40603306, 2025).
type 2 diabetes (14 papers, 2012 to 2024). "Furthermore, Hspa5 was found increased in the pancreas of type 2 diabetes patients, indicating increased endoplasmic reticulum stress during this disease, and in a microarray-based gene expression study, Itpkc was found to be insulin-regulated." (PMID 25333294, 2015). "However, experimental studies are required to reproduce these molecular consequences of HSF1 deficiency and to draw definitive conclusions about the causal relationship between the HSF1 gene, molecular chaperones HSP90B1, HSPA5, and FKBP4, and impaired proinsulin folding in type 2 diabetes." (PMID 36431071, 2022).
Alzheimer disease (12 papers, 2011 to 2025). A progressive, neurodegenerative disease characterized by loss of function and death of nerve cells in several areas of the brain leading to loss of cognitive function such as memory and language. "HSP90, HSPA5, and LYN are implicated in key Alzheimer’s disease pathologies, including neuroinflammation and disrupted protein homeostasis." (PMID 40732226, 2025). "Novel candidates are associated with neurodegenerative disorders including Alzheimer's disease (VSNL1), prion disease (SCRG1, HSPH1, HSPA5 and CTR9) and age-related degeneration (GAS6 and GNG11)." (PMID 21569303, 2011). "Nilotinib’s strong positive connectivity with HSP90, HSPA5, and LYN suggests repurposing potential for Alzheimer’s disease." (PMID 40732226, 2025).
bladder cancer (12 papers, 2013 to 2025). "In bladder cancer and lung squamous cell carcinoma, the expression of HSPA5 was associated with disease development and prognosis." (PMID 39194522, 2024). "It was reported that HSPA5 is upregulated in bladder cancer tissues and functions as oncogene in bladder cancer." (PMID 40765821, 2025). "The number of TUNEL-positive apoptotic nuclei was significantly reduced in SBSPON/HSPA5-overexpression bladder cancer cells compared to the SBSPON overexpression cells." (PMID 40765821, 2025). "However, the roles and underlying mechanisms of HSPA5 in bladder cancer remain unclear." (PMID 40765821, 2025). "SBSPON inhibited bladder cancer progress by suppressing the AKT signal pathway through inhibiting HSPA5 membrane translocation." (PMID 40765821, 2025). "More importantly, SBSPON inhibited the cisplatin resistance of bladder cancer cells by reducing the inhibitory effect of HSPA5 on apoptosis." (PMID 40765821, 2025). "The results showed that SBSPON-overexpressing reduced HSPA5 protein level in the membrane fraction in bladder cancer cells." (PMID 40765821, 2025). "Overall, this study highlighted the significant finding that SBSPON could modulate ER stress signaling by interacting with HSPA5 and further enhanced apoptosis following chemotherapy in bladder cancer by promoting ER stress-induced cell death." (PMID 40765821, 2025). "Furthermore, SBSPON could attenuate HSPA5's inhibitory effect on ER stress-mediated cell death in bladder cancer after DDP treatment." (PMID 40765821, 2025). "For instance, HSPA5 has been recently shown to serve as a prognostic marker that promotes the proliferation and metastatic spread of the disease by regulating ferroptosis in bladder cancer, whereas KDELR2 enhances Golgi-mediated secretion to promote bladder cancer growth and metastasis." (PMID 40026699, 2025). "Other independent studies have highlighted the role of RPN1, HSPA5, and YIF1B as prognostic markers of the disease along with other sets of genes in bladder cancer." (PMID 40026699, 2025). "Considering the cellular location of SBSPON, we investigated the interaction between HSPA5 and ER sensors PERK in bladder cancer cells using a Co-IP assay." (PMID 40765821, 2025). "We also discovered that ER stress component, like HSPA5, ERN1, ATF4 and DDIT3, increased when the human bladder cancer cells were treated with BIX-01294." (PMID 25685062, 2015). "The overexpression of SBSPON can significantly counteract the growth promotion and the inhibition of apoptosis of HSPA5 overexpression on bladder cancer cells when treated with DDP and TM, while the overexpression of HSPA5 had the opposite effects on bladder cancer cells with overexpressed SBSPON." (PMID 40765821, 2025). "Moreover, SBSPON could modulate ER stress signaling through competitively binding HSPA5 with ER sensors PERK under ER stress and further potentiate apoptosis during chemotherapy treatment for bladder cancer through the induction of ER stress." (PMID 40765821, 2025).
triple-negative breast carcinoma (12 papers, 2014 to 2025). An invasive breast carcinoma which is negative for expression of estrogen receptor (ER), progesterone receptor (PR), and human epidermal growth factor receptor 2 (HER2). "Additionally, HSPA5 expression has been correlated with tumor grade and metastatic events in triple negative breast carcinoma (TNBC) and is functionally relevant to clinical progression." (PMID 25857301, 2015).
astrocytoma (11 papers, 2012 to 2025). "Compared with HIV-1CladeC gp120 in astrocytoma, HIV-1CladeB gp120 can induce the expression of HSPA5 and other ER stress markers, and HIV-1Tat can also induce HSPA5 and other ER stress markers." (PMID 36845091, 2023).
Cognitive impairment (11 papers, 2018 to 2025). Abnormal cognition is characterized by deficits in thinking, reasoning, or remembering. "Animal experiments have shown that mice in the A/S group exhibited cognitive impairments accompanied by increased Hspa5 and Xbp1 expression, ER stress, and activation of NLRP3 inflammasome." (PMID 39432407, 2024). "Anesthesia and surgery‐induced upregulation of Hspa5 and Xbp1 gene expression subsequently led to ER stress, NLRP3 inflammasome activation, and neuroinflammation, potentially contributing to cognitive deficits in aged mice." (PMID 39432407, 2024).
Hypertension (11 papers, 2010 to 2024). The presence of chronic increased pressure in the systemic arterial system. "Meanwhile, NONRATG012674.2, which is overexpressed in the high salt sensitivity group, could interact with key hypertension genes like Anxa8, Hspa5, and Krt15, with Hspa5 being part of the HSP70 family associated with hypertension and inflammation." (PMID 38791545, 2024). "Hspa5 is a member of the heat shock protein 70 (HSP70) family, which is correlated with inflammatory markers of essential hypertension." (PMID 31886193, 2019).
myocardial infarction (11 papers, 2011 to 2022). Gross necrosis of the myocardium, as a result of interruption of the blood supply to the area, as in coronary thrombosis. "More specifically, targeting Hspa8 and Hspa5 has been demonstrated to protect cardiomyocytes and mesenchymal stem cells from hypoxia-induced apoptosis, whereas delivering these heat shock proteins into transplanted mesenchymal stem cells rescues heart function after myocardial infarction in rats." (PMID 21569252, 2011).
Cerebral ischemia (10 papers, 2012 to 2025). Restriction of arterial blood supply to the brain associated with insufficient oxygenation to support the metabolic requirements of the tissue. "Furthermore, Park7 could inhibit ferroptosis in cerebral ischemia-reperfusion injury via the Atf4/Hspa5 pathway." (PMID 39343514, 2024).
ZIKV infection (10 papers, 2018 to 2025). "HSPA5 KD decreased HSPA5 expression by 5-fold and the KD remained stable in the presence of ZIKV infection." (PMID 36680137, 2022). "Remarkably, the temporal behavior of a few genes is inconsistent with the global transcriptomics shifts: for instance the expression of HSPA5 increases until 24 hr after ZIKV infection, but is then sharply decreased at 48 hr post-infection and with higher intracellular virus abundance." (PMID 29451494, 2018). "Among the other temporally regulated genes in ZIKV infection, is the circadian clock gene PER2 that resembles HSPA5." (PMID 29451494, 2018). "HSPA5 KD decreased HSPA5 expression by 8-fold compared to the scrambled siRNA treatment by 3 hpi, irrespective of the presence of ZIKV infection." (PMID 36680137, 2022). "Three robust patterns were identified: genes, such as HSPA5, that were upregulated in DENV infection and downregulated in ZIKV and VEEV infections; genes like NRBF2 that were upregulated only during ZIKV infection; and genes, such as SERP1, that were downregulated only in VEEV infection." (PMID 33788849, 2021). "HSPA5 is included in this list, in agreement with its t-SNE visualization; this gene is therefore not only subject to opposite regulation in DENV versus ZIKV infection, but may play different roles at different times during the same infection." (PMID 29451494, 2018).
acute lymphoblastic leukemia (9 papers, 2013 to 2023). Leukemia with an acute onset, characterized by the presence of lymphoblasts in the bone marrow and the peripheral blood. "HSPA5 is highly expressed in B-lineage acute lymphoblastic leukemia (ALL) and its expression increases at relapse." (PMID 37221596, 2023).
autoimmune disease (9 papers, 2010 to 2025). A disorder resulting from loss of function or tissue destruction of an organ or multiple organs, arising from humoral or cellular immune responses of the individual to their own tissue constituents. "The Ddit3 and Hspa5 results are especially intriguing as depletion of DDIT3 has been shown to exacerbate disease in PMD animal models, while reduction of HSPA5 is deleterious to oligodendrocyte survival in both normal and autoimmune disease contexts and is depleted in PMD models." (PMID 30146490, 2018).
oral cancer (9 papers, 2014 to 2022). "The clinical oncogenesis roles of HSP90AA1 and HSPA5 in oral cancer have been reported." (PMID 31222140, 2019). "HSPA5 is a potential biomarker for detection and treatment of oral cancer patients." (PMID 31222140, 2019). "Moreover, sEV derived from oral cancer cells contained a variety of HSPs, including HSP90α (HSP90AA1), HSP90β, TRAP1 (mitochondrial HSP90), HSP105, HSP70 (HSP72/HSPA1A and HSP70B’/HSPA6), GRP78/HSPA5 (ER chaperone), and HSC70." (PMID 32204513, 2020).